TLR7 (toll like receptor 7)
Diseases named in the same sentence as TLR7 in open-access papers (continued):
Sharing a sentence is not in itself a finding about the gene and the disease.
COVID-19 (continued). "A TLR7/8 antagonist, Enpatoran (M5049), is a potent dual TLR7/8 inhibitor that is expected to cease the hyperinflammatory milieu in symptomatic patients with COVID-19." (PMID 35832809, 2022). "Although this association was suggested by previous studies, our study provides the most definitive evidence for the role of TLR7 in COVID-19 pathogenesis, with exome-wide significance for this gene in the discovery phase followed by strong replication in a large independent cohort." (PMID 36327219, 2022). "Besides TLR7, inborn errors of type I IFN immunity were found as well to be implicated in the development of a severe form of COVID-19." (PMID 35618891, 2022). "Of specific interest, we observed that carrying a predicted loss of function or in-silico highly deleterious missense variant (i.e., mask M3) in the toll-like receptor 7 (TLR7) gene was associated with a 5.3-fold increase (95% CI: 2.7–10.1, p = 5.41x10-7) in odds of severe COVID-19." (PMID 36327219, 2022). "The potential that the ATM deficit influenced the progression of COVID-19 in the TLR7-deficient case cannot be ruled out." (PMID 37521843, 2022). "Given the recent finding that 1.8% of men below the age of 60 who develop life-threatening COVID-19 have a defective TLR7, there may also be other connections of importance for how CD21low B-cells interact with SARS-CoV-2 vaccines." (PMID 35290571, 2022). "Of note, none of the sequenced A-T patients with or without COVID-19 (n = 29, including 4 of remaining HIgM patients with asymptomatic/mild presentation) carried variants in the TLR7 gene." (PMID 34686943, 2022). "This is significant because TLR7/8 activation of NF-κB increases cytokine production and, in conjunction with inflammasome activity, NF-κB drives an axis of IL-1β, IL-6, IL-12, TNFα, and Th1 T-cell hyperinflammation as part of COVID-19 immunopathology." (PMID 35261923, 2022). "We will also present a possible connection between COVID-19 and SS through TLR7, and precent recent therapies that target the nucleic acid-sensing TLRs that might prove to be a novel strategy for preventing and or treating SS disease." (PMID 36389822, 2022). "Whole-genome sequencing of SARS-CoV-2 in comparison with other coronaviruses (MERS-CoV and SARS-CoV) has revealed that TLR7 could be significantly involved in COVID-19 as the viral genome contains more ssRNA motifs that can bind to TLR7." (PMID 36142620, 2022). "Moreover, the TLR7 agonists imiquimod and imidazoquinolinone (with a role in TLR7activation) are under investigation as potential therapeutics against COVID-19." (PMID 36142620, 2022). "TLR7/8 may also recognize antiphospholipid antibodies (aPL), which have been shown to be upregulated in patients with severe and critical COVID-19." (PMID 36419185, 2022). "In a nested case study, it was found that the loss-of-function mutation of TLR7 is present in 2.1% of the patients with severe COVID-19, but in none of the asymptomatic patients." (PMID 35847031, 2022). "TLR7 agonist imiquimod has been proposed as a possible therapeutic for COVID-19." (PMID 35847031, 2022). "Due to some intriguing connections with autoimmunity, it is also reasonable to suspect that TLR7/8 signaling following tissue damage could contribute to COVID-19 immunopathology." (PMID 35261923, 2022). "Rare putative loss-of-function variants of X-chromosomal TLR7 were detected in young men (age < 35 years) without preexisting medical conditions affected by severe COVID-19." (PMID 34718937, 2022). "Here, we provide a hypothesis that females may be protected to some extend against severe COVID-19, due to the biallelic TLR7 expression, allowing them to mount a stronger and more protective IFN response early after infection." (PMID 34858409, 2021). "In particular, this hypothesis and theory article focuses on TLR7 expression and activation and the consequences for males and females in COVID-19." (PMID 34858409, 2021).
COVID-19 (continued). "TLR7 agonists have been proposed as treatment, which may prevent the onset of severe COVID-19 in symptomatic patients and even synergize with active antiviral therapy such as remdesivir." (PMID 34858409, 2021). "Evidence is mounting that rare loss-of-function variants in the TLR7 gene predispose men with no medical history to severe forms of COVID-19." (PMID 33752797, 2021). "This article proposed a hypothesis that XCI escape of TLR7 and the resulting gene-dose effect in females is beneficial in COVID-19." (PMID 34858409, 2021). "If ER signaling indeed enhances TLR7 signaling, the menopausal estrogen drop could mean that the protective effect of increased TLR7 signaling in females would be partly lost and the female sex bias in COVID-19 would be diminished." (PMID 34858409, 2021). "It has been suggested that TLR agonists, including imiquimod, an immune stimulator of TLR7, could serve as an effective therapeutic approach in the early stages of COVID-19 and could be more favorable." (PMID 34835108, 2021). "This could be attributed to an increase in TLR7/8 recognizing antiphospholipid antibodies (aPL) (a TLR7/8 activating DAMP) in COVID-19 patients." (PMID 34770863, 2021). "This study supports a rationale for the genetic screening for TLR7 variants in young men with severe COVID-19 in the absence of other relevant risk factors." (PMID 34367187, 2021). "A case-series article identified four young men from two families carrying rare and inactivating mutations in TLR7 who suffered from severe COVID-19 in the absence of common comorbitidies." (PMID 33859644, 2021). "TLR1, TLR4, TLR5, TLR8, and TLR9 expression levels were also significantly elevated in severe and critical COVID-19 patients; however, TLR3 expression was not correlated with the development of COVID-19, and an increased expression of TLR7 was observed only in patients with moderate COVID-19." (PMID 34835108, 2021). "In this respect, there would be a strong argument to offer hemizygous TLR7 deficient males that have not had COVID-19 direct access to early vaccination as an effective preventative measure, similar to other patients with primary immunodeficiencies." (PMID 34367187, 2021). "Based on observations made relating to SARS-CoV-1, hyperinflammatory responses to COVID-19 may also be owing to TLR7 and TLR8 activity." (PMID 33498725, 2021). "The clinical penetrance of critical COVID-19 in men is therefore high, but not complete, and TLR7 deficiency can also underlie severe COVID-19." (PMID 34413140, 2021). "To conclude, there are clear indications for an X chromosomal TLR7 gene-dose effect in COVID-19." (PMID 34858409, 2021). "XCI escape of TLR7 and subsequent increased expression of type 1 IFN could be part of the immunological explanation for the observed sex differences concerning severe COVID-19 susceptibility." (PMID 34858409, 2021). "TASL has not been associated with COVID-19 directly, but indirectly via its adaptor function in the TLR7-mediated IFN pathway." (PMID 34858409, 2021). "TLR7, a Toll-like kind of receptor, which is higher in females than males, could enhance immune responses and boost the resistance to COVID-19." (PMID 33939733, 2021). "In total, these three reports describe eight rare TLR7 variants in 12 male patients with no medical history who still developed severe COVID-19." (PMID 33752797, 2021). "Moreover, the TLR7 agonist, Imiquimod, is proposed as candidate to manage early stage COVID-19 patients." (PMID 33519463, 2020). "As for the X-chromosomal TLR7 gene, the mono-allelic versus the bi-allelic presence of this gene too may have an adverse impact on the natural history and prognosis of COVID-19 in males." (PMID 33092637, 2020). "Recently, TLR7 has been found to be important also in the immune response to COVID-19." (PMID 33255528, 2020). "The role of TLR3 and TLR7 in the pathogenesis of COVID-19 is discussed in the study by Sallenave." (PMID 32604797, 2020).
COVID-19 (continued). "Moreover, TLR7 and TLR8, which have been implicated in inflammasome signaling have been suggested to play an underlying role in COVID-19 severity." (PMID 33149733, 2020). "A recent genetic analysis of young cases of severe COVID-19 has revealed decreased type I and type II IFN responses in the absence of TLR7 expression due to a 4-nucleotide deletion or a missense mutation within the X-chromosomal TLR7 gene." (PMID 33062077, 2020). "However, owing to the lack of lung autopsy or biopsy samples from TLR7-deficient COVID-19 patients, the effect of TLR7 signaling or a lack thereof on lung inflammation and pathology is not known." (PMID 40162785, 2025). "TLR7 can activate innate immune responses, potentially negatively influencing the tumor microenvironment and cancer cell behavior.The inflammatory response to COVID-19 may have a short-term protective benefit that wanes over time." (PMID 40853959, 2025). "Additionally, given the similar disease outcomes in control, TLR7−/−, and IFNAR-deficient MA-CoV-2-infected mice and coronavirus disease 2019 (COVID-19) patients, we propose that MA-CoV-2-infected mice constitute an excellent model for studying COVID-19." (PMID 40162785, 2025). "In conclusion, TLR7 might be essential in the pathogenesis of COVID-19 and cancers." (PMID 37362864, 2023). "To gain insight into TLR7-linked mechanisms of severe COVID-19, we performed RNA sequencing (RNA-Seq) to carefully characterize transcriptome variations following IMQ stimulation of peripheral blood mononuclear cells (PBMC) isolated from patients carrying previously identified LOF TLR7 variants." (PMID 34952932, 2022). "As a result, TLR7 activation might play controversial roles during COVID-19 progression." (PMID 35538443, 2022). "In addition to GWAS and the associated data, TLR7 located in the X chromosome was considered a potential monogenic cause that predisposed young male patients without comorbidities to severe COVID-19." (PMID 36292769, 2022). "In addition, mutations in TLR3 and TLR7 might be playing a role in SARS-Co-V-2 disease outcomes: in-born errors in TLR3 and IRF7 were associated with disease severity and mortality in COVID-19 patients." (PMID 35336937, 2022). "In addition, genetic variations in TLR7 that located on the X chromosome, may be a possible explanation of the sex biases in COVID-19 severity." (PMID 36204639, 2022). "Moreover, other studies on SARS-CoV-2 have revealed the pathological role of TLR4 and TLR7/8 in excessive inflammatory response in COVID-19 patients as it leads to the formation of neutrophil extracellular traps (NETs) and the activation of inflammasomes, leading to acute lung injury." (PMID 35832809, 2022). "We therefore further investigated the WES data for additional genetic defects that might be related to the severe COVID-19 presentation in this patient and identified a novel hemizygous mutation in the TLR7 gene (c.1114C > A, p.Leu372Met)." (PMID 34686943, 2022). "Moreover, several studies have shown that an overwhelming TLR7 response may promote the development of severe COVID-19, highlighting the clinical importance of the TLR-mediated immune response during SARS-CoV-2 infection." (PMID 35832809, 2022). "To evaluate the functionality of the innate immune cells in COVID-19, we performed ex vivo stimulation of whole blood with different pathogen-associated molecular patterns (PAMPs): bacterial LPS, a TLR4 ligand; R848, a synthetic ligand for TLR7/8; and Pam3CSK4 (PAM), a synthetic ligand for TLR1/2." (PMID 35380990, 2022). "Our data could serve as a basis for future studies leading to the design of new therapeutic options, e.g. the generation and/or optimization of novel sequence-tailored TLR7/8 agonists and/or antagonists, and further targeted immunomodulation-based therapies for COVID-19 patients." (PMID 36713399, 2022).
COVID-19 (continued). "In order to investigate whether lower availability of ADO could contribute to the pro-inflammatory profile of COVID-19, MNCs from patients with severe COVID-19 and HDs were cultured with a TLR7/TLR8 agonist (CL097, imidazoquinoline-derived compound) under the presence or absence of ADO." (PMID 36248842, 2022). "Therefore, genetic screening for TLR7 primary immunodeficiency was recommended in young males with severe COVID-19 in the absence of other relevant risk factors." (PMID 34858409, 2021). "Accumulating evidence suggests that rare loss-of-function mutations in a single gene known as TLR7 could predispose men under 50 without known risk factors to severe COVID-19." (PMID 33752797, 2021). "It has also been postulated that activation of TLR7 could be effective against COVID-19." (PMID 34067609, 2021). "Although these mutations are unlikely to be an explanation for severe COVID-19 in the general population, other mechanisms accounting for TLR7 signaling impairment could result in a similar situation." (PMID 33859644, 2021). "Most striking was the under-expression of genes involved in viral recognition (e.g. TLR7, UNC93B, RIG-I/DDX58), as well as genes encoding downstream signaling molecules and transcription factors (e.g. TRIF/TICAM1, MYD88, IRF7), with the notable exception of IRF4, in COVID-19 compared to INFL." (PMID 34135895, 2021). "They reported rare loss-of-function variants of the X-chromosomal Toll-like receptor 7 (TLR7), with immunological defects in type I and II interferon production probably due to the aberrant function of peripheral blood mononuclear cells in severe COVID-19 patients." (PMID 34976886, 2021). "Therefore, these rare TLR7 variants are unlikely to be an explanation for severe COVID-19 in the general population." (PMID 34367187, 2021). "Besides the TLR7 gene-dose effect caused by XCI escape, other biological differences between the sexes may influence the sex bias observed in COVID-19." (PMID 34858409, 2021). "Interestingly, it was recently discovered that individuals carrying germinal mutations in genes active in toll-like receptor 7 (TLR7) among young men with severe COVID-19 confirming an important role of type I and II IFN responses in the pathogenesis of COVID-19." (PMID 33357238, 2020). "CpG-55.2, another TLR9 agonist, and imidazoquinolin, a TLR7/8 agonist, have also been formulated as adjuvants in EUA COVID-19 vaccines." (PMID 40495154, 2025). "To assess the contribution of TLR7, TYK2 and OAS1 expression to COVID-19 progression over time, we conducted a longitudinal study on the expression of these three genes in patients with COVID-19." (PMID 41445728, 2025). "In COVID-19, the induction of a cytokine storm is mainly regulated by TLR3, TLR4, TLR7, and TLR8 and triggers an excessive inflammatory response, leading to severe disease and death." (PMID 39940907, 2025). "-Neutrophils from patients with severe COVID-19 exhibit higher levels of TLR3 and TLR7 than those from healthy donors.-TLR3 gene expression was found to be significantly higher in critically ill SARS-CoV-2 patients than in those with mild disease." (PMID 41011507, 2025). "Additionally, given the similar disease outcomes in SARS-CoV-2-infected controls and TLR7-deficient/mutant individuals and responses to anti-IFN/IFNAR antibodies in mice and humans, our results further support the use of a mouse model and mouse-adapted SARS-CoV-2 to study COVID-19 pathogenesis." (PMID 40162785, 2025). "Our findings of how a natural ligand of TLR7, miRNA let-7b, is suppressed by SARS-CoV-2 RBPs will advance our understanding of COVID-19 and SARS-CoV-2 therapeutics." (PMID 40590376, 2025). "We observed decreased expression of the viral receptors TLR7 and ACE2 in the epidermis of COVID-19 patients compared to HCs." (PMID 40649826, 2025). "In summary, our results showed that TLR7 signaling is protective during SARS-CoV-2 infection in mice, similar to that observed in humans with COVID-19." (PMID 40162785, 2025).
COVID-19 (continued). "Studies have shown that mutations in genes related to the immunological response, including Toll-Like Receptor 7 (TLR7) and Unc-13 Homolog D (UNC13D), correlate with adverse COVID-19 consequences." (PMID 40002898, 2025). "Neutrophil extracellular traps (NETs), which are actively formed in severe COVID-19 patients, can also activate various pattern recognition receptors, including TLR4 and TLR7, thereby facilitating the release of inflammatory mediators." (PMID 39457048, 2024). "TLR7 and TLR8 agonists potentiate the Th1 but suppress the Th2 immune response, an event which is beneficial for COVID-19 vaccines." (PMID 38390874, 2024). "TLR3 (p < 0.001), TLR7 (p < 0.001), and TLR8 (p < 0.001) expression levels were considerably greater in COVID-19 patients compared to the control group." (PMID 38868379, 2024). "Here, we observed that, at admission, COVID-19 patients had a low response to the agonist of TLR2, TLR4, TLR7/8, and TLR9, suggesting a TLR cross-tolerance." (PMID 37189696, 2023). "Given that mature neutrophils express all TLRs except TLR3, we analyzed the expressions of TLR7, TLR8 and TLR9 in normal human neutrophils after being treated with EVs from COVID-19 patients (n = 6) and HC subjects (n = 6), respectively." (PMID 37904132, 2023). "Another study reported decreased functioning of DCs from COVID-19 patients towards TLR triggers during acute SARS-CoV-2 infection as DC activation upon TLR3, TLR4, TLR7 and TLR8 triggering was suppressed." (PMID 37844099, 2023). "Therefore, genetic screening for TLR7 primary immunodeficiency may be recommended in young males with severe COVID-19 in the absence of other relevant risk factors." (PMID 37175768, 2023). "Studies of innate activation unrelated to COVID-19 are also very limited, revealing TLR1, TLR2, TLR3, TLR4, TLR7 and TLR8 activation." (PMID 36769320, 2023). "Having observed differential expression of type III and II IFNs in the lower respiratory tracts of COVID-19 patients, we evaluated TLR expression in BALs; in particular, deceased patients showed lower expression levels of TLR7 and TLR8 mRNAs." (PMID 36985262, 2023). "With the activation of TLR-7 and TLR-9 in COVID-19 mRNA vaccines, there are more alterations with pro-inflammatory cytokines such as interleukin 1 (IL-1) and interleukin 6 (IL-6)." (PMID 37091488, 2023). "There was a significant upregulation of mRNA of TLR3 (fold change = 2.9, P = 0.011), TLR7 (fold change = 2.2, P = 0.020), TLR8 (fold change = 2.9, P = 0.040), and TLR9 (fold change = 2.5, P = 0.001) in COVID-19-Group A in comparison to the Control-Group II." (PMID 35538443, 2022). "There was a significant positive correlation between LDH level and mRNA expression of TLR3 (rho = 0.39, P = 0.041), TLR7 (rho = 0.41, P = 0.008), and TLR8 (rho = 0.49, P = 0.030) in the whole COVID-19 cases." (PMID 35538443, 2022). "There was a significant upregulation of mRNA of TLR3 (fold change = 2.4, P = 0.017), TLR7 (fold change = 2.0, P = 0.009), TLR8 (fold change = 2.2, P = 0.004), and TLR9 (fold change = 2.9, P = 0.010) in COVID-19-Group B compared with the Control-Group III." (PMID 35538443, 2022). "There was a significant upregulation of mRNA of TLR3 (fold change = 2.1, P = 0.022), TLR7 (fold change = 1.9, P = 0.025), TLR8 (fold change = 2.0, P = 0.039), and TLR9 (fold change = 2.9, P = 0.024) in COVID-19-Group B compared with the Control-Group I." (PMID 35538443, 2022). "Third, while the largest biobanks contributed the most to the signal observed at TLR7 and MARK1, many of our smaller prospective COVID-19 specific cohorts also contributed to the signal." (PMID 36327219, 2022). "Incubation with the TLR7/TLR8 agonist induces the production of TNF-α and IL-6 in cells from HDs and COVID-19 patients." (PMID 36248842, 2022).